TLR4 (toll like receptor 4)
Diseases named in the same sentence as TLR4 in open-access papers (continued):
Sharing a sentence is not in itself a finding about the gene and the disease.
myocardial infarction (continued). "In the current study, myocardial and serum levels of TNF- α in rats fed with high-fat diets and isoproterenol-induced myocardial infarction animals were evaluated to clarify the correlation between TLR4/MyD88 protein expressions in myocardium and production of proinflammatory cytokines." (PMID 32211137, 2020). "TLR4/NF‐κB pathway has been involved in the inflammatory response related to other cardiovascular diseases, such as acute myocardial infarction and targeting this pathway was suggested to offer an effective therapeutic approach to preserve function of ischaemic heart in patients." (PMID 32860486, 2020). "Moreover, clinical studies have shown that TLR4 expression in peripheral blood mononuclear cells is extremely elevated in patients with myocardial infarction and even higher at the site of the plaque rupture." (PMID 32751587, 2020). "Furthermore, to compare the effect of a high level of LDL and oxidized LDL on inflammatory pathways following myocardial infarction we also assessed TLR4 expression and activity in the heart." (PMID 32211137, 2020). "Furthermore, in a mouse model of myocardial infarction, TNF-α mRNA, IL-1α, IL-2, IL-4, IL-5, IL-6, IL-10, IL-17A, TNF-α, IFN-γ, and GM-CSF expression were all lower in the infarct area of TLR4-deficient mice compared with wild-type mice." (PMID 30399158, 2018). "The treatment of short hairpin RNA (shRNA) for TLR4 decreased inflammatory cytokine production, fibrotic area, and left ventricle infarct size and recovered fractional shortening of the left ventricle in a rat myocardial infarction (MI) model." (PMID 30116150, 2018). "In addition, blockade with TLR4 antagonists has been shown to have a beneficial effect in myocardial infarction." (PMID 25692136, 2015). "In this context, patients with acute coronary syndromes or coronary arteriosclerosis showed increased TLR4 expression on circulating monocytes, compared with control patients; high expression of TLR4 was also found at the site of ruptured plaques in patients with acute myocardial infarction." (PMID 25757594, 2015). "TLR4 is also activated by several endogenous ligands associated with tissue injury such as High-Mobility Group Box 1 Protein (HMGB1), HSP60/70, and hyaluronan in response to myocardial infarction (MI)." (PMID 26030867, 2015). "TLR4 is over-expressed in ruptured plaques in patients with acute myocardial infarction." (PMID 26492242, 2015). "In the heart, TLR2 and TLR4 are perhaps involved in the host response to myocardial infarction." (PMID 23889805, 2013). "Similarly, eritoran, a synthetic lipid-A analogue which inhibits TLR4 signaling, was beneficial in a mouse model of myocardial infarction." (PMID 22577589, 2012). "Using a murine model involving permanent coronary ligation in wild-type and TLR4-mutant mice, Timmers and colleagues investigated whether TLR4 is involved in ventricular remodeling after myocardial infarction." (PMID 20676278, 2009). "In addition to the NF‐kB and TLR4 signalling pathways, several alternative cascades may contribute to myocardial infarction and high‐fat diet induced fibrosis and remodelling." (PMID 41387361, 2025). "Moreover, TLR4 amplifies heart failure after long-term myocardial infarction." (PMID 39065537, 2024). "Moreover, another study showed that nicorandil could alleviate pyroptosis in rats with myocardial infarction by influencing the TLR4/MYD88/NF-κB/NLRP3 pathway." (PMID 38095638, 2023). "Interestingly, several clinical and pre-clinical studies have shown a critical role of the innate immune receptor, Toll-like receptor 4 (TLR4), in cardiovascular disease conditions such as acute myocardial infarction, ischemic heart injury, heart failure, dilated cardiomyopathy, and septic shock." (PMID 37239362, 2023).
myocardial infarction (continued). "Many previous reports showed that expressions of TLR2, TLR3, and TLR4 as proatherogenic receptors were related to the extent and severity of coronary heart disease and led to the development of the atherosclerotic lesions, atherosclerotic arterial occlusions, and acute myocardial infarction." (PMID 35425840, 2022). "In compliance with these results, in rats with myocardial infarction, the treatment of adipose-derived stromal cells-derived exosomes containing miR-93-5p showed a protective effect in rats with myocardial infarction, targeting Atg7 and Toll-like receptor 4 (TLR4)." (PMID 33573156, 2021). "Consequently, a myocardial infarction could result in activation of the TLR4-NF-κB signaling pathway in the myocardium and, therefore, induce inflammation and cardiac dysfunction." (PMID 32751587, 2020). "Inhibition of the high-mobility group box-1 (HMGB1)/TLR4/TRAF6/NF-κB signaling pathway is beneficial for treatments of MI/R injury and acute myocardial infarction (AMI)." (PMID 32038243, 2019). "Notably, numerous studies have demonstrated that TLR4 activates the expression of several of pro-inflammatory cytokine genes that play pivotal roles in myocardial inflammation, particularly myocarditis, myocardial infarction, ischemia-reperfusion injury, and heart failure." (PMID 27228349, 2016). "TLR4 contributes to myocardial infarction by inducing a systemic and a myocardial cytokine response after MI/R." (PMID 17592640, 2007). "QL also down-regulates the Toll-like receptor 4 (TLR4)/NF-κB signaling pathway and up-regulates the TGF-β3/Smad7 signaling pathway, thereby attenuating cardiac remodeling after myocardial infarction." (PMID 40881586, 2025). "Luteolin downregulates the expression of TLR4, MyD88, and NF-κB in a dose-dependent manner to inhibit NLRP3 inflammasome activation, consequently diminishing myocardial infarct size and enhancing left ventricular function." (PMID 39925805, 2025). "MiR-16 is a down-regulated target of Toll-like receptor 4 (TLR4) and has been found to be upregulated in patients with acute myocardial infarction." (PMID 37330548, 2023). "HSPB1 knockout mice subjected to myocardial infarction (MI) exhibited enhanced and prolonged leukocyte infiltration, enhanced inflammatory cytokine expression, and enhanced toll-like receptor 4 (TLR4)/myeloid differentiation factor 88 (MyD88)/NF-κB activation in their heart tissue." (PMID 37252119, 2023). "Additionally, they promoted cardiac function in mice with myocardial infarction (MI), inhibited the inflammatory response, and inactivated the TLR4/NF-κB signaling pathway." (PMID 37941898, 2023). "This research sought to investigate the clinical significance of level changes of TLR2, TLR3, TLR4, TNF-α, sTNFR-1, sTNFR-2, EPCs, and VEGF in elderly patients with recurrent myocardial infarction after coronary stent implantation." (PMID 35425840, 2022). "Gain- and loss-of-function experiments were performed to evaluate the effect of the circ_SMG6/miR-138-5p/EGR1/TLR4/TRIF axis on cardiac functions, myocardial infarction, myocardial enzyme levels, cardiomyocyte activities, and neutrophil recruitment." (PMID 35126807, 2022). "For example, depletion of TLR4 attenuates myocardial infarction injury, whereas activation of TLR2, or TLR4, or TLR5 impairs CMs contractility." (PMID 34206257, 2021). "In conclusion, our results demonstrated that danshen ameliorates inflammatory injury by controlling MD2/TLR4‐MyD88 complex formation and TLR4‐TRAF6‐NF‐κB signalling pathway in acute myocardial infarction‐induced HF." (PMID 32757377, 2020). "Our results showed that ISO-induced myocardial infarction is accompanied by significant escalations in levels of the TLR2, TLR4, MyD88, and TRIF, enhancing subsequent inflammatory mediator signaling." (PMID 31109132, 2019).
myocardial infarction (continued). "β-Caryophyllene at doses of 100 and 200 mg/kg lessened post- myocardial infarction TLR activity measured as the protein content of TLR2 (A), TLR4 (B), MyD88 (C), and TRIF (D) in the heart tissue (p < 0.05)." (PMID 31109132, 2019). "On the other hand, miR-327 was reported to indirectly suppress the TLR4 and TLR2 signaling pathways, and subsequently resulted in reduced myocardial infarct size and alleviated inflammation." (PMID 30513647, 2018). "In particular, TLR-4 and its downstream targets such as TNF-α and i-NOS are found to facilitate the inflammatory reaction in clinical ischemic condition, i.e. myocardial infarction." (PMID 30356256, 2018). "Myocardial infarct sizes, histological scores, levels of circulating and myocardial IL-6 and TNF-α, the expression of HMGB1, TLR4, MyD88 and NF-κB, and the degradation of IκB were significantly increased in the I/R group compared with the sham group (P<0.01)." (PMID 28222157, 2017). "In this study, we investigate the diverse influence of PRDX2 on TLR4 and VEGF in myocyte hypertrophy and acute myocardial infarction (AMI) from data acquired through clinical trials, H9c2 cells and in a mouse model system." (PMID 28765537, 2017). "Previous studies observed TLR4‐mediated inflammation within days of myocardial infarction (MI)." (PMID 26290459, 2015). "Post-myocardial infarction, exosomal miR-146a from transfected ADSCs directly suppressed early growth response factor 1 (EGR1) activation and IL-1β/-6 and TNF-α expression due to inhibition of the toll-like receptor 4 (TLR4)/NF-κB pathway." (PMID 40676634, 2025). "BYHWD down-regulated IL-18, NLRP3 inflammatory vesicles, and TLR4/NF-κB signaling pathway by inhibiting the TLR4 signaling pathway, and suppressed the expression level of collagen I/III, thereby attenuating cardiac inflammation and myocardial fibrosis after myocardial infarction." (PMID 40881586, 2025). "TLR4 and TLR2 activation following myocardial ischemic injury triggers the NF-kappa B pathway and subsequent expression of pro-inflammatory genes, inducing an inflammatory cascade, increasing myocardial infarction size, and impacting cardiac remodeling." (PMID 39024234, 2024). "Toll-like receptor 4 (TLR4) is an integral factor in the initiation of the innate immune response and plays an important role in cardiovascular diseases such as hypertension and myocardial infarction." (PMID 37034342, 2023). "In addition, the LDH and CK activity in arterial blood as well as myocardial infarct size and cardiomyocyte apoptosis was attenuated upon EGR1 silencing or TLR4/TRIF inhibition." (PMID 35126807, 2022). "Levels of TLR2, TLR3, TLR4, TNF-α, sTNFR-1, and sTNFR-2 were remarkably increased (P < 0.001), and EPCs and VEGF were remarkably lowered (P < 0.001) in the elderly patients with recurrent myocardial infarction after coronary stent implantation." (PMID 35425840, 2022). "It suppresses p38 MAPK signaling pathway, and reduces arrhythmogenesis following myocardial infarction, and enhances cardiac function.It inhibits the expression of TLR4, MyD88, GM-CSF, IL-1β, TNF-α, and COX-2, and attenuates LPS-mediated TLR4-NF-κB pathway activation." (PMID 33868227, 2021). "TLR4, TLR2, MyD88, and TRIF protein levels via western blot in the heart tissue were measured following ISO-induced myocardial infarction to determine whether β-caryophyllene could suppress TLR activity through MyD88 down-regulation." (PMID 31109132, 2019). "In this paper, we summarise the current state of knowledge linking TLR2 and TLR4 to I/R injury, including recent studies which demonstrate that therapeutic inhibition of TLR2 has beneficial effects on I/R injury in a murine model of myocardial infarction." (PMID 20628516, 2010).
myocardial infarction (continued). "As a result of weak GMA intervention, the expression of TLR4, TRAF6, NF-κB, and TNF-α was significantly decreased, the expression of MyD88 and MCP-1 was increased, the inflammatory response was blunted, the area of myocardial infarction was reduced, and cardiac function was improved." (PMID 38197985, 2024). "Interestingly, TLR4 knockout MSCs maintained their expression of CD47 (a “don’t eat me” signal), increasing their survival and facilitating their protective effects in a pre-clinical model of myocardial infarction." (PMID 34831203, 2021). "Recently we demonstrated that TLR4 and MyD88 were increased in brainstem of myocardial infarction (MI)-induced heart failure, and that intracerebroventricular (ICV) injection of angiotensin II type 1 receptor blocker prevented LV remodeling with sympathoinhibiton and reduction of TLR4 in brainstem." (PMID 23874864, 2013).
Cognitive impairment (140 papers, 2011 to 2026). Abnormal cognition is characterized by deficits in thinking, reasoning, or remembering. "It has been demonstrated that infusing S protein into the mouse brain causes delayed cognitive deficits but the early TLR4 inhibition effectively prevents impairments to synapses and memory." (PMID 41011507, 2025). "LPS activates the microglia via TLR4, switching them to a pro-inflammatory phenotype via the NF-κB pathway, causing neuroinflammation and cognitive impairment." (PMID 41516244, 2025). "Microglial TLR4 loss-of-function mutations also increase Aβ deposits and exacerbate cognitive deficits." (PMID 41292987, 2025). "In conclusion, Mor blocks the TLR4/NF-κB pathway, reducing hippocampal tissue damage and neuroinflammation caused by Sev, which in turn improves cognitive impairment in aged mice." (PMID 39670511, 2025). "In conclusion, our study demonstrates that repeated neonatal sevoflurane exposure induces transient microglial activation and TLR4/NF-κB-mediated neuroinflammation, which are associated with long-term cognitive deficits in adolescent rats." (PMID 41281895, 2025). "Chronic consumption of alcohol can be a cause of neuroinflammation via activation of TLR-4 in microglial cells, which can directly or indirectly contribute to the development of brain damage and cognitive impairment." (PMID 38473876, 2024). "Polymorphisms of the GG genotype of TLR4 2604G>A (rs10759931) are associated with a greater risk of developing cognitive impairment following SARS-CoV-2 infection than the GA genotype." (PMID 38891900, 2024). "From this analysis for example, we identified TLR4 antagonists as repurposing candidates with potential to protect against long term cognitive impairment pathology caused by SARS-CoV-2." (PMID 37915075, 2023). "Following intracerebral hemorrhage, TLR4 is activated via the MyD88 signaling pathway causing brain oxidative injury and cognitive impairment." (PMID 36523959, 2022). "Lipopolysaccharide (LPS) and high-mobility group box 1 (HMGB1) are Toll-like receptor (TLR4) agonists that activate proinflammatory neuroimmune signaling linked to loss of basal forebrain cholinergic neurons (BFCNs) and cognitive deficits." (PMID 36072299, 2022). "Taken together, these findings provide evidence that acupuncture attenuates cognitive impairment associated with inflammation through inhibition of the miR-93-mediated TLR4/MyD88/NF-κB signaling pathway in experimental VD." (PMID 32850002, 2020). "Increased brain HMGB1 levels have been associated with cognitive deficits, effects that are mediated through both TLR4 and RAGE receptors." (PMID 30687006, 2018). "TLR2/4−/− mice are protected from cognitive impairment following Aβ immunisation with polymorphism in the tlr2 and tlr4 gene linked with AD." (PMID 23671673, 2013). "On this basis, it was further explored whether Mor alleviated cognitive impairment caused by Sev through hindering the TLR4/NF-κB pathway." (PMID 39670511, 2025). "Consequently, we focused on examining the impact of FMT on the hippocampal TLR4/IKKβ/NF‐κB signaling pathway to gain insight into the underlying mechanisms of its neuroprotective effects against cognitive deficit in 5 × FAD mice." (PMID 39957504, 2025). "Furthermore, patients with mild SARS-CoV-2 infections who had the GG genotype of the TLR4-2604G>A variant exhibited increased TLR4 expression and were at a higher risk of cognitive impairment than those with the GA genotype." (PMID 41011507, 2025). "Furthermore, TLR4 has been shown to play a significant role in cancer-associated cognitive impairment." (PMID 38891900, 2024). "Furthermore, elevated TLR4 expression in the brain tissue and peripheral blood of Alzheimer’s disease patients has been linked to the progression of cognitive impairments." (PMID 38887610, 2024). "Interestingly, TLR4 deficiency was found to protect against sevoflurane-induced cognitive impairment and inflammation in mice." (PMID 38891900, 2024).